CD4 (CD4 molecule)
Diseases named in the same sentence as CD4 in open-access papers (continued):
Sharing a sentence is not in itself a finding about the gene and the disease.
Opportunistic infection (continued). "Infection with the human immunodeficiency virus (HIV) results in progressive loss of immune function marked by depletion of the CD4 + T-lymphocytes, leading to opportunistic infections and AIDS-defining cancers such as Kaposi’s sarcoma, non-Hodgkin lymphoma, and invasive cervical carcinoma." (PMID 36566196, 2022). "Once, the virus penetrates the host, it destroys the function of immune cells like helper T cells specifically CD4 + T cells, macrophages, and dendritic cells, reducing the significant number of CD4 cell count and subsequently it leads to an increased number of opportunistic infections in PLHA." (PMID 35672713, 2022). "IRIS is a well-known phenomenon in HIV disease that results from rapid rises in CD4+ T cell counts after successful antiretroviral therapy and may manifest as strong responses to opportunistic infections when pathogen immunity is restored by antiretroviral therapy." (PMID 36452901, 2022). "We analyzed whether clinical biomarkers such as age, gender, baseline CD4 count, baseline HIV viral load, acute HIV infection, HCV/HBV coinfections, comorbidities and opportunistic infections impacted the rate of CD4 cell count recovery and CD4:CD8 ratio recovery." (PMID 36298842, 2022). "The other argument is that therapy with more than one tablet daily might lead to poor adherence, which leads to poor outcomes in terms of virological suppression, CD4 increase, and opportunistic infection prevention, eventually leading to regimen discontinuation." (PMID 34863200, 2021). "Sustained reduction of CD4+ counts occurred in this trial; however, investigators also noted that the addition of prednisone during the induction may have contributed to the high incidence of opportunistic infections, including PJP." (PMID 34155819, 2021). "However, it can become an invasive disease with the involvement of deep tissue and/or visceral organs such as lungs, gastrointestinal tract, liver, and spleen, with CD4 cells count <200 cells/mL and possible opportunistic infection occurring; in this case, it is defined as stage T1." (PMID 34831094, 2021). "It was therefore not possible to conduct heterogeneity analyses to test whether healthcare expenditures were particularly high among standard of care group participants with potential opportunistic infections and CD4 counts close to (but above) the treatment cutoffs." (PMID 33834318, 2021). "This might be attributed to the likelihood of opportunistic infection that follows a low CD4 level." (PMID 34306251, 2021). "Variables that were associated include base line chronic disease, number of opportunistic infections at base line, base line and recent functional status, base line and recent WHO clinical stage, base line and recent hemoglobin level, and base line and recent CD4 count." (PMID 34972122, 2021). "Thus, the lower potential of the CD4 count scale-up of the AZT-based regimen might lead patients to develop opportunistic infections, which ultimately insist declaration of immunologic antiretroviral treatment failure." (PMID 32462003, 2020). "Consequently, low CD4 count coupled with not starting ART would expose HIV infected patients for higher risk of different opportunistic infections including, cryptococcosis." (PMID 32527231, 2020). "Other observational studies have found that opportunistic infections, presence of chronic diarrhea, low baseline hemoglobin level, poor adherence to drugs, poor functioning status, and low body mass index (BMI) at baseline were significantly allied with weak CD4 count shifts." (PMID 32476985, 2020). "The observation that the Muse Auto CD4/CD4% is small but precise and accurate instrument is encouraging and instruments like the Muse could be used to monitor HIV disease and to screen patients for the risk of opportunistic infections." (PMID 30673713, 2019).
Opportunistic infection (continued). "A recent report from Malaysia indicates that in addition to not using ART and a CD4 ≤ 200 (aHR: 3.89, 95%CI: 1.20 – 12.63), having three or more opportunistic infections (aHR: 3.61, 95%CI: 1.04 – 12.53) are risk factors for mortality in TB/HIV co-infected individuals." (PMID 31892929, 2019). "Counselling should stress the importance of early CTC, whether or not the client has a good CD4 count or feels healthy, to allow close monitoring of the client and prophylaxis for opportunistic infections, to avoid a drop in CD4 count and allow timely initiation of medication." (PMID 30114244, 2018). "Evidence suggests that non-adherence in advanced HIV disease may be as a result of increased opportunistic infections and HIV complications requiring many medicines to treat these conditions.The immunological status (CD4+ cell count) of women was also linked with adherence to ART in pregnancy." (PMID 29945601, 2018). "In addition, CD4+ levels play an important role to protect the host from opportunistic infections." (PMID 29155831, 2017). "CD4 counts are also used to decide on prophylaxis against opportunistic infections, for instance to screen for cryptococcal infection in patients with ≤ 100 CD4 cells/μL and stop prophylaxis when patient presents with > 200 cells/μL, or start co-trimoxazole in case CD4 counts are ≤ 350 cells/μL." (PMID 28129324, 2017). "Finally, although low CD4+ T-cell count and high viral load are, separately, strongly correlated with an increased risk of opportunistic infections and mortality, these measures do not necessarily equate with disease." (PMID 26951820, 2016). "Daily fluctuations in CD4 counts and fluctuations induced by opportunistic infections are common, so this may have led to another misclassification, in two directions: regarding some persons unfairly as immunological non-responders and others unfairly as immunological responders." (PMID 27438000, 2016). "Confounders included baseline CD4 count, study visit, gender, age, education level, marital status, alcohol consumption, monthly income, smoking status, diagnosis of depression, social support, presence of opportunistic infection, WHO disease stage, religion, and employment status." (PMID 26370702, 2015). "The proportion of patients with low duration on ART had a high occurrence of ocular manifestations compared to their counterparts because ART drugs may have a role in increasing the CD4 counts and boosting the immunity status of patients which reduce the occurrence of opportunistic infections." (PMID 26000175, 2015). "Immediate access to CD4 T cells results may also enable more rapid initiation of prophylactic treatment for opportunistic infections as well as chemotherapy for prevention of mother-to-child transmission at sites where CD4 T lymphocytes levels define the prophylactic drug regimen." (PMID 23631664, 2013). "These observed findings could be attributed to the use of HAART which inhibits HIV viral replication and allows for CD4 T cell related immune reconstitution that could have protected the participants against opportunistic infections at all stages of HIV disease." (PMID 24312650, 2013). "However, ICL patients with severe opportunistic infections had CD4+ T cell counts <200/mm3." (PMID 23383227, 2013). "Given no clear association between lower baseline CD4 counts and KS progression, it is possible that opportunistic infections may have contributed to deaths more than progressive KS during the study period." (PMID 22496970, 2012). "Micronutrient interventions that aim to improve CD4 cell count, decrease opportunistic infections, decrease HIV viral load, and ultimately delay initiation of more costly ART may be beneficial, particularly in resource-constrained settings, such as sub-Saharan Africa." (PMID 21838913, 2011).
Opportunistic infection (continued). "One recent retrospective review found an increased risk of death or opportunistic infection among women stopping therapy after delivery, but the group was more heterogeneous than in the current study with 46% having previous ARV exposure and 36% having a pre-ARV CD4+ cell count below 350 cells/uL." (PMID 19893751, 2009). "Importantly, if microbial stimuli such as plasma LPS are drivers of immune activation and ultimately contribute to CD4 T cell decline and HIV disease, then viral suppressive therapy would only be expected to have limited or delayed affect on CD4 recovery and prevention of opportunistic infections." (PMID 19461969, 2009). "For several years, scientists have speculated that susceptibility to a given opportunistic infection might be due not simply to low total CD4+ cells, but to loss of the specific CD4+ cells that recognize the infection in question." (PMID 17388662, 2007). "CD4 testing is recommended to identify individuals with advanced HIV disease to facilitate timely screening and prophylaxis for opportunistic infections." (PMID 41566892, 2026). "Only rarely do patients have normal or near-normal CD4 counts, indicating that PCM most often behaves as an opportunistic infection." (PMID 41494000, 2026). "Toxoplasma gondii encephalitis is a common but serious opportunistic infection in people living with human immunodeficiency virus (PLHIV), particularly those with advanced disease and low CD4 counts." (PMID 41658715, 2026). "Multinomial logistic, logistic, and negative binomial regression models were used to identify predictors of discordant responses, severe CD4/CD8 ratio inversion, and opportunistic infection burden." (PMID 42198715, 2026). "Clinically, the decrease in CD4+ T cells and CD4+/CD8+ T cell ratio in the tacrolimus group correlated with a case of opportunistic infection, underscoring the importance of immune monitoring during treatment." (PMID 41169356, 2025). "He showed improvement after receiving TMP-SMX, with instructions to continue it until his CD4 count improves with appropriate ART to prevent reinfection with PCP and other opportunistic infections." (PMID 40677426, 2025). "The opportunistic infections group demonstrated reduced lymphocyte counts (LYM) and lower T-cell subset levels, including CD3+T cell counts, CD4+T cell counts and CD8+T cell counts." (PMID 39866736, 2024). "As is known, CD4 cell count is a significant parameter predicting HIV progression, opportunistic infections and death in HIV-infected individuals, as well was an important indicator for initiating antiretroviral therapy (ART)." (PMID 38778273, 2024). "The difference in outcomes for patients on the second‐line regimen may be due to factors such as CD4 count progression, lack of nutritional support, and treatment adherence issues leading to viral resistance and increased susceptibility to opportunistic infections." (PMID 38562614, 2024). "However, experimental infections demonstrated the ability of hypervirulent CCoV types to induce systemic disease with acute lymphopenia or subsequent prolonged depletion of peripheral CD4+ T cells, which theoretically may lead to a potential exposure to opportunistic infections." (PMID 40303143, 2024). "Key risk factors for the development of IRIS include the presence of disseminated opportunistic infections at the time of ART initiation and a low baseline CD4+ T cell count, typically below 50 cells/μL." (PMID 39830540, 2024). "Different variables (age, sex, time in therapy with BIC-STR, time in ART pre-switch, previous opportunistic infections, HCV or HBV coinfections, comorbidities more than one, nadir CD4 count, zenith HIV-RNA) were included in the univariate analysis." (PMID 38131882, 2023). "HIV RNA levels measure viral load and CD4 count provides an indication of immune function in people living with HIV (PLHIV) and is one of the key determinants for determining need for opportunistic infection (OI) prophylaxis." (PMID 37805465, 2023).
Opportunistic infection (continued). "For this reason, we focused on the opportunistic infections faced by HIV patients and the correlation of these infections with the CD4/CD8 ratio and HIV viral load in the present study." (PMID 37887742, 2023). "Five percent had an opportunistic infection at baseline; the median pre‐ART CD4 count was 338 (IQR 187–498) cells/mm3." (PMID 36943729, 2023). "Given the high prevalence of depressed CD4+-T-cells in RRMM patients, prophylaxis against opportunistic infections should be generously considered in all RRMM patients." (PMID 37152008, 2023). "Meanwhile, the depletion of CD4+ T cells induced by HIV and consequent opportunistic infections and co-infections have increased the prevalence of uveitis as an HIV-related ocular complication." (PMID 36851658, 2023). "Authors stated that total lymphocyte, CD3+, CD4+ and CD8+ T cells and NK-cell counts at month 1 were significantly decreased in patients who subsequently developed an opportunistic infection between the 1st and 6th month after KT." (PMID 37515152, 2023). "The frequency of opportunistic infections in the patients was related to their CTCC and CD4/CD8 ratios." (PMID 38102603, 2023). "Most patients with other opportunistic infections (talaromycosis, PCP infection, bacterial pneumonia, septicemia, CMV infection, and toxoplasmosis) had CD4 counts < 50 cells/mm3." (PMID 35042469, 2022). "Even when the CD4 count remains low, suppressive ART helps prevent opportunistic infections and other HIV related complications." (PMID 35456055, 2022). "Unfavorable trends in CD4+ lymphocyte counts are an indication of drug failure and suggest a change in the HAART regimen or intensification of opportunistic infection prophylaxis before new clinical events." (PMID 36147157, 2022). "Fungi contribute significantly to opportunistic infections in people living with HIV (PLWH), especially in immunocompromised patients with low CD4 + T-cell counts." (PMID 36016433, 2022). "Patients with a low CD4 count or advanced WHO stage have reduced immunity and are thus sicker and more prone to opportunistic infections." (PMID 35448827, 2022). "Idiopathic CD4 + T lymphocytopenia (ICL) is a rare immunodeficiency syndrome, unaccompanied by various opportunistic infections." (PMID 35248113, 2022). "The frequency of opportunistic infections was 21%, rising to 30.3% in patients with advanced HIV disease (<200 CD4); 8.1% of these patients had more than one infection." (PMID 36547618, 2022). "The depleting CD4+ T cells count is a marker of immune dysfunction and HIV progression and indicators of acquiring multiple opportunistic infections and co-infections." (PMID 35239716, 2022). "According to the guidelines for opportunistic infection of HIV by the National Institute of Health (NIH), MAC typically occurs in PLWHA with CD4+ T cell count <50 cells/mm3 and plasma HIV RNA level >1,000 copies/mL." (PMID 36355915, 2022). "Low viral suppression was common in patients with weakened immune systems, who present with opportunistic infections, on WHO stages III or IV and/or a low CD4 count (< 200 cells/μL) upon initiation on ART." (PMID 36226955, 2022). "While we excluded cases with other brain pathology or opportunistic infections, the group as a whole shows advanced HIV (median CD4 count, 70 cells/μL)." (PMID 32722761, 2021). "As in-vitro stimulation alone may not predict the susceptibility of select patients to opportunistic infections, measuring thymic output and diversity of the CD4 and CD8 TCR repertoire may also offer predictive value given the para-thymic nature of this syndrome." (PMID 35095915, 2021). "Low CD4 counts, WHO clinical stage, opportunistic infection, rural residence, and being female in gender were found to have a significant association with the occurrence of food insecurity among adult people with HIV at the national level." (PMID 34159189, 2021).
Opportunistic infection (continued). "A previous work observed a correlation between CD4+ and CD19+ cell counts with opportunistic infections after auto-HSCT." (PMID 34659226, 2021). "They all presented with fever, cough and breathlessness and also had advanced HIV infection as evidenced by opportunistic infections, high HIV viral loads and low CD4 counts." (PMID 33976453, 2020). "TNF-α: tumor necrosis factor-alpha, OI: opportunistic infection, HCV: hepatitis C virus, HIV: human immunodeficiency virus, CD4: cluster of differentiation-4." (PMID 33209528, 2020). "A lower CD4 cell count, sex, age, advanced HIV diseases, presence of opportunistic infections, adherence concern, inability to access food and having social support were also significantly associated with malnutrition." (PMID 32163485, 2020). "Base-line opportunistic infection, duration on first-line ART, NVP based ART, Baseline CD4 count level, OI after ART initiation, and time it takes to reach health facility were independent determinants of first-line ART treatment failure." (PMID 33175902, 2020). "CD4 count is an indicator of immune function in PLWH and one of the key determinants for the need of opportunistic infection prophylaxis." (PMID 33777501, 2020). "In a recent study, 21% of people with newly-diagnosed HIV in Freetown had a CD4 cell count below 100 cells/mm3, suggesting a need for earlier HIV testing, particularly given the limited resources for managing opportunistic infections." (PMID 32059703, 2020). "HIV related clinical factors such CD4 count, WHO stage, opportunistic infection, antiretroviral therapy regimen etc. were collected from the medical records." (PMID 32549993, 2020). "In fact, according to national guidelines, CD4 count is required for all newly HIV-diagnosed patients in order to decide starting and discontinuing the prophylaxis of opportunistic infections, for patient with late presentation." (PMID 32522235, 2020). "Idiopathic T-CD4 lymphocytopenia (ICL) is a rare and heterogeneous syndrome characterized by opportunistic infections due to reduced CD4 T-lymphocytes (<300 cells/μl or <20% T-cells) in the absence of HIV infection and other primary causes of lymphopenia." (PMID 31781092, 2019). "After controlling /adjusting other variables like (sex, alcohol abuse, religion, educational status, CD4 count, drug abuse, duration with ART, medication adherence, monthly income, comorbid illness, opportunistic infection history)." (PMID 30883557, 2019). "They cited the need for a CD4 ‘baseline’ for patients initiating ART and they felt that ongoing CD4 monitoring was required to measure the need for OI (opportunistic infection) prophylaxis, ART response and a switch in treatment regimens." (PMID 30764808, 2019). "Opportunistic infections are found frequently in HIV positive patients, especially when the CD4 T-cell count is less than 200 cells/μl." (PMID 31110984, 2019). "Cotrimoxazole prophylactic therapy is a recommended prophylaxis of opportunistic infections in patients with severe or advanced HIV clinical disease (WHO stage 3 or 4) and/or for a CD4 count ≤ 350 cells/mm3." (PMID 30042677, 2018). "The review found that low CD4 count; advanced stage of the disease (WHO clinical stage III &IV), opportunistic infection and low level of BMI were found to have positive significant association with the development of anemia." (PMID 30459953, 2018). "A lower number of CD4 cells/μl (1/1, 100%), a higher HIV stage (1/1, 100%), a higher HIV load (1/1, 100%), the presence of opportunistic infections (1/1, 100%) and a higher BMI (1/1, 100%) were negatively associated with physical activity." (PMID 30602967, 2018). "CD4 testing is recommended at baseline for all patients starting treatment, and also to manage advanced HIV disease and opportunistic infections in unstable patients on treatment." (PMID 30231022, 2018).